OR52P2P (olfactory receptor family 52 subfamily P member 2 pseudogene)
Gene: Unitary pseudogene on chromosome 11 (4,431,323 to 4,432,277, reverse strand). Ensembl gene ENSG00000171999.
Diseases named in the same sentence as OR52P2P in open-access papers:
OR52P2P is named in the same sentence as 1 disease in open-access papers, as found by Europe PMC text mining. Sharing a sentence is not in itself a finding about the gene and the disease. The quoted sentences say what the papers report.
bacterial meningitis (1 paper, 2024). Inflammation of the membranes surrounding the brain and spinal cord due to a bacterial infection. "In this study, CCR5, KIF5C, OR52P2P, OR52K2, and OR51R1P were co-expression with lncRNA AC091138.1 in bacterial meningitis specific co-expression networks." (PMID 38347610, 2024). "In bacterial meningitis patients, 8 co-expression relationships were constructed between 8 mRNAs (ACBD7, OR52K2, GPR68, SHISA4, KIF5C, OR52P2P, OR51R1P, and CCR5) and 1 lncRNA." (PMID 38347610, 2024).